MMP9 (matrix metallopeptidase 9)
Diseases named in the same sentence as MMP9 in open-access papers (continued):
Sharing a sentence is not in itself a finding about the gene and the disease.
Cerebral ischemia (continued). "MMP-9 does not exist in the central nervous system but can be detected after cerebral ischemia and breakdown of the blood–brain barrier (BBB), eventually leading to neuronal death." (PMID 39850789, 2024). "In patients with acute MI, complicated with cerebral ischemia (CI) confirmed in cerebral computed tomography (CT), the levels of MMP-2 and MMP-9 as well as MMP-2 and MMP-9 mRNA expression were significantly higher in comparison with patients with MI, but without CI." (PMID 36835040, 2023). "Animals and patient studies have discovered that cerebral ischemia can induce expression of MMPs, particularly, the increased activity of MMP-2 and MMP-9, which is closely related to increased cerebral microvascular permeability, BBB destruction, inflammatory cell invasion, and brain edema." (PMID 35317197, 2022). "A study on cerebral ischemia in rats also postulates that HMGB-1 can upregulate the expression of MMP-9 although this mechanism has not been determined in the pancreas." (PMID 35041718, 2022). "For instance, the degradation of matrix proteins in the vascular basal lamina by MMP9, leading to BBB disruption, has been suggested to contribute to the brain damage that occurs following cerebral ischemia, effects that can be attenuated through MMP9 inhibition." (PMID 34034683, 2021). "In a cerebral ischemia injury model, FABP4 promotes MMP-9 expression through JNK/c-Jun signaling." (PMID 34685761, 2021). "For example, both MMP2 and MMP9 downregulated ZO-1 expression and enhanced BBB permeability in response to focal cerebral ischemia-reperfusion injury, but MMP9 deficiency did not reduce disruption of the BBB during viral encephalomyelitis." (PMID 33859779, 2021). "Three in MMP family members, MMP2, MMP9 (referred to as the gelatinases), and MMP3, are thought to be activated within the ischemic lesion where they are critical to injury progression during and after cerebral ischemia." (PMID 30723388, 2019). "If so, MMP‐9 raises the permeability of BBB by degrading ECM so as to promote vasogenic cerebral edema, increase inflammatory cell infiltration, and promote inflammatory reaction and apoptosis, which aggravates cerebral ischemia/reperfusion." (PMID 31566928, 2019). "Evidences found that the expression and activity of MMP‐9 in the ischemic brain tissue increased significantly in the early stage of cerebral ischemia/reperfusion, while MMP‐2 showed no significant change (Liu, Hendren, Qin, & Liu, 2009)." (PMID 31566928, 2019). "In humans and rodents with cerebral ischemia/reperfusion (I/R), the SUR1 antagonist, glibenclamide, reduces hemorrhagic transformation and plasma MMP-9, but the mechanism is unknown." (PMID 29617457, 2018). "MMP-9, and MMP-2 played the most prominent role in cerebral ischemia." (PMID 29681849, 2018). "Whereas expressions of VEGF, MMP-9, and TGF-β were undetectable in the brains of sham-operated rats, significant expressions of VEGF, MMP-9, and TGF-β were observed in the border area within the ischemic core and penumbra at 28 days after cerebral ischemia (21 days after transplantation)." (PMID 28195185, 2017). "Moreover, astragalus polysaccharides and saponins can inhibit MMP-9 expression and enhance TIMP1 expression after cerebral ischemia/reperfusion (I/R) injury in mice." (PMID 28831024, 2017). "However, during the acute phase of cerebral ischemia, the infiltrated leukocytes and reactive microglia synthesize and secrete MMPs (mainly MMP-2 and MMP-9) and ROS, thus increasing BBB permeability." (PMID 27703487, 2016). "For instance, in a mouse model of focal cerebral ischemia, the deletion of the TIMP-1 gene results in increased MMP-9 protein expression and gelatinolytic activity, and is accompanied by exacerbated BBB disruption, neuronal apoptosis and ischemic injury when compared to wild-type animals." (PMID 25741233, 2015).
Cerebral ischemia (continued). "The neuroprotective effects of the angiotensin receptor antagonists are well documented in experimental cerebral ischemia, but their robust vascular protective effects appear to be incompatible with the demonstrated ability to increase MMP-2 and MMP-9 activity." (PMID 25147751, 2014). "This preconditioning of rt-PA, however, also did not lead to the 2–4fold increase of the cerebral ischemia-induced MMP-9 activity in the ischemic hemisphere that has been reported elsewhere for the filament occlusion model." (PMID 24499647, 2013). "Although MMP-9 inhibition or KO can attenuate proteolysis of BBB, more recent studies suggest its possible role in neurovascular regeneration, especially in the delayed phase of cerebral ischemia." (PMID 23565108, 2013). "Although MMP-9 inhibition or knockout can attenuate proteolysis of BBB, more recent studies suggest its possible role in neurovascular regeneration, especially in the delayed phase of cerebral ischemia." (PMID 22587708, 2012). "Silencing/inhibition of MMP-9 and PARP-1 both reduce damage after cerebral ischemia." (PMID 22235301, 2012). "The expression of MMPs, especially MMP2, MMP9 and MMP10, is induced by cerebral ischemia." (PMID 21541054, 2011). "The expressions of MMP-9 and MMP-2 are elevated after cerebral ischemia and able to open the BBB." (PMID 20514206, 2009). "Silencing of miR-21, but not miR-224, reduced MMP9 protein levels after cerebral ischemia." (PMID 38987854, 2024). "Notably, in the brains of rats with Parkinson’s disease and cerebral ischemia, MMP-9 not only co-localizes with AQP4 but also an increase in MMP-9 expression results in altered AQP4 polarity, (i.e., “depolarization”), MMP-9 disturbs aquaporin-4 polarization by cleaving β-dystroglycan." (PMID 39295943, 2024). "Thus, among the gelatinases, MMP-9 may play a greater role in BBB disruption and poor neuronal outcomes after cerebral ischemia and r-tPA treatment." (PMID 39273389, 2024). "There was no significant change in ZO-1 expression (a tight junction protein modulated by MMP-9) between control and cKO mice in response to 2h-ischemia/4h-reperfusion, indicating the critical role of MMP-2/occludin pathway in neuronal ZnT3-modulaed BBB disruption in response to cerebral ischemia." (PMID 37962463, 2023). "Ten minutes of global cerebral ischemia followed by 24 hours of reperfusion induces changes in the expression of NOX2 subunits and MMP9 and changes of the oxidative stress parameters in the brain, as well as the increase in MMP9 activity in the serum of experimental animals." (PMID 29849881, 2018). "In cerebral ischemia, neutrophils are believed to comprise a critical source of MMP-9 responsible for hemorrhagic transformation, but other cell types intrinsic to the brain, including neurons, microglia, pericytes and endothelial cells also express MMP-9 (see review)." (PMID 29617457, 2018). "Thus, in the present study, we sought to investigate the effects of XXMD on cerebral ischemia and reperfusion injury and to determine whether XXMD could attenuate BBB disruption by inhibiting the expression of MMP-9, MMP-2, and VEGF." (PMID 23710225, 2013). "Furthermore, MMP-9 knockout models or treatment with MMP tissue inhibitors, synthetic MMP inhibitors and MMP neutralizing antibodies have been shown to protect blood-brain barrier (BBB), reduce vaso-genic edema formation and infarct size after cerebral ischemia." (PMID 20514206, 2009). "We found that, unlike MMP-9, MMP-2 was constantly expressed at low levels in the brain tissue of both wild-type and gp91phox knockout mice, and its expression was not affected by cerebral ischemia and reperfusion or gp91phox knockout." (PMID 22146586, 2011).
Cerebral ischemia (continued). "In the present study, we found an increase in both MMP-2 and MMP-9 mRNA and a clear increase in MMP-9 activity in Poldip-2+/+ mice but not in Poldip2+/− mice, implying that reduction in MMP activity may contribute to the reduced BBB permeability in Poldip2+/− mice after cerebral ischemia." (PMID 29452577, 2018).
asthma (206 papers, 2003 to 2026). "In this current study, we found an association between higher MMP‐9 levels at birth and lower risk of bronchiolitis in the first year of life, as well as reduced asthma incidence at six years." (PMID 40952045, 2026). "MMP‐9 levels were inversely associated with both the risk of bronchiolitis hospitalization (odds ratio 0.47, [0.29; 0.77], padj = 0.004) and the risk of asthma (aOR 0.53, 95% CI, 0.32–0.86, padj = 0.033)." (PMID 40952045, 2026). "Using logistic regression adjusting for confounders, we also found a protective effect of higher MMP‐9 on asthma in childhood risk (aOR 0.53, 95% CI, 0.32–0.86, padj = 0.033)." (PMID 40952045, 2026). "Although MMP-9 has been extensively linked to asthma severity, as its levels in sputum and lung tissue correlate with disease severity, our study did not observe changes in MMP-9 following IL-5 stimulation." (PMID 41188935, 2025). "While MMP‐2 and MMP‐9 are implicated in asthma, MMP‐9, MMP‐1, MMP‐13, MMP‐2, and MMP‐8 have been shown to be extensively involved in the progression of UC." (PMID 40568744, 2025). "MMP9 is closely associated with a variety of allergic diseases, including allergic nasal polyps, asthma, allergic bronchopulmonary aspergillosis, atopic dermatitis, pollen allergy, and others." (PMID 38974913, 2024). "Although the roles of MMP-7 and MMP-10 in asthma are still being elucidated, MMP-9 has shown consistent associations with disease severity and airway remodeling processes." (PMID 38275403, 2024). "Neutrophilic cytokines, including Tgfb, Tnfa, Cxcl15, Elane, and Mmp9, also showed significantly reduced expression in Poly(I:C)-induced asthma exacerbation mice after CUL5 deficiency." (PMID 38177117, 2024). "The expression of HSPA1A, PIK3CG and PIK3R6 was associated with moderate asthma, while MAPK13 and MMP9 were associated with severe asthma." (PMID 39088141, 2024). "Members of the MMP family, especially the gelatinases MMP-2 and MMP-9, have been implicated in pulmonary inflammation and asthma, ALI, and pulmonary fibrosis." (PMID 37763673, 2023). "An imbalance of the MMP9/TIMP ratio is associated with the pathogenesis of asthma and lung diseases." (PMID 35379891, 2022). "Another important mediator involved in asthma is the family of extracellular proteases represented by matrix metalloproteinase 9 (MMP-9), causing tissue remodeling through destruction of extracellular structures." (PMID 35631208, 2022). "Low sputum MMP-9/TIMP2 ratios are associated with airway narrowing in smokers with asthma and MMP-9/TIMP-1 ratios correlate inversely with airway wall thickness assessed by CT scanning in asthmatics." (PMID 33718297, 2021). "MMP-9 was among the first to be implicated in asthma pathogenesis, where abundant MMP-9 mRNA expression was noted in submucosal regions of asthmatic bronchial biopsies when compared to normal subjects, especially within the eosinophils in asthmatic tissues." (PMID 33628848, 2021). "Numerous studies have shown that MMP-9 is involved in asthma and is associated with the gradual remodeling of the airway walls." (PMID 33126646, 2020). "It is worth noting that pivotal differences in exhaled MMP-9 levels were detected in mild/moderate eosinophilic, severe eosinophilic, and severe neutrophilic asthmatics, indicating an association between asthma severity and airway remodeling." (PMID 32054098, 2020). "Higher levels of MMP-9 are associated with increased asthma severity and decreased lung functioning." (PMID 31653934, 2019). "Published data on the association between MMP-9 polymorphisms (−1562 C > T, rs3918242; Gln279Arg, rs17576 Arg668Gln, rs17577) and asthma susceptibility are inconclusive." (PMID 30931075, 2019). "There are few association studies between other polymorphisms of MMP-9 gene and asthma susceptibility." (PMID 30931075, 2019). "Murine models of asthma in MMP-9-deficient animals have confirmed the involvement of MMP-9 in peribronchial fibrosis." (PMID 26123447, 2016).
asthma (continued). "MMP-9-deficient animals exhibit reduced airway inflammation, and the immunoreactivity of MMP-9 has been demonstrated to be associated with the severity of asthma." (PMID 26783416, 2016). "They include the analysis of protein levels, nucleotide polymorphisms of MMP-9 gene and their possible correlation with asthma and COPD." (PMID 26123447, 2016). "Matrix metalloproteinase 9 (MMP-9) from neutrophils has been shown to be associated with asthma severity." (PMID 26011707, 2015). "The airway remodeling in asthma is associated with increased amount of matrix metalloproteinase (MMP)-9." (PMID 25650123, 2015). "MMP9 immunoreactivity has been demonstrated to be associated with the severity of classic asthma and MMP9-deficient animals exhibit reduced airway inflammation." (PMID 25187823, 2014). "IL-1β and MMP-9 promote subepithelial fibrosis, subepithelial collagen deposition and elastin fibre disruption in asthma and in COPD are associated with many of the histopathological features of emphysema." (PMID 23398985, 2013). "Similar to MMP-9, SP-D is thought to be involved in the mechanism behind the pathology of many pulmonary diseases, including asthma, smoking-associated respiratory problems, COPD, IPF, and cystic fibrosis." (PMID 22860023, 2012). "MMP-9 in particular appears to play a role in chronic airway inflammation and remodeling in asthma, and in a murine asthma model is upregulated in association with the accumulation of inflammatory cells." (PMID 23029210, 2012). "In addition, we found that lower MMP‐9 was associated with the risk of bronchiolitis hospitalization in the first year of life and asthma in childhood." (PMID 40952045, 2026). "Additionally, adults with asthma show deficient MMP‐9 release in response to bacterial proteins that stimulate neutrophil migration compared to healthy controls." (PMID 40952045, 2026). "A meta-analysis showed that MMP9 polymorphisms was associated with asthma risk." (PMID 41150507, 2025). "Future studies could investigate the effect of long‐term EC use on MMP‐9 and IL‐6 levels to determine if consumers are at increased risk for related diseases such as asthma, rheumatoid arthritis, or cancer." (PMID 38353387, 2024). "Genes IFNG and MMP9 were associated with Airway Inflammation in Asthma." (PMID 35812753, 2022). "Eventually, we identified 7 case-control publications, including 1592 asthma patients and 1987 controls, to evaluate the association of MMP-9 polymorphisms (including three SNPs: −1562 C > T, rs3918242; Gln279Arg, rs17576; and Arg668Gln, rs17577) with asthma susceptibility." (PMID 30931075, 2019). "The present meta-analysis suggests that MMP-9 Arg668Gln, rs17577 polymorphism may be the risk factor for asthma susceptibility." (PMID 30931075, 2019). "In addition, in the coding region of MMP-9 gene, the association of Gln279Arg, rs17576 and Arg668Gln, rs17577 polymorphisms with the susceptibility of asthma was also assessed." (PMID 30931075, 2019). "The other reason may be this mutant allele has small effects, but tightly linked to other possibly functional polymorphisms within MMP-9 or other genes involving in the inflammatory response which play more fundamental roles in asthma." (PMID 30931075, 2019). "In addition, Gln279Arg, rs17576 and Arg668Gln, rs17577 polymorphic variants augment activity of MMP-9 in children with asthma." (PMID 30931075, 2019). "Therefore, a lot of genetic epidemiology studies have assessed the association of MMP-9 gene polymorphisms and susceptibility of asthma in different populations." (PMID 30931075, 2019). "Therefore, to understand the causal relationship of MMP-9 and M1/M2 macrophage activation in the development of airway remodeling in asthma, the macrophage polarization in BAL and airway tissue should be addressed in future studies." (PMID 31547356, 2019).
asthma (continued). "Moreover, the high level of MMP-9 expression in bronchial biopsies from asthmatic patients was associated with asthma severity as well as the number of macrophages and neutrophils." (PMID 31547356, 2019). "Previous reports revealed that MMP-9 increases in severe asthma, and that it may be the cause of airflow obstruction through the induction of airway structural changes." (PMID 31547356, 2019). "Elevated expression of MMP-9 is associated with severe asthma and a decline in pulmonary functions." (PMID 30360392, 2018). "Furthermore, a functional study suggested that MMP-9 polymorphisms were associated with increased asthma pathogenesis." (PMID 27637086, 2016). "Besides sarcoidosis, other respiratory diseases, including chronic obstructive pulmonary disease (COPD), asthma, and idiopathic interstitial pneumonia (IIPs), are associated with a similar elevation of some pro-inflammatory factors and MMPs (e.g.MMP-9)." (PMID 27575817, 2016). "Rho kinase may also be involved in eotaxin and cytokine (IL-5, IL-13) production and in secretion of matrix metalloproteinase – 9 (MMP-9), tightly associated with fibrosis in asthma and chronic obstructive pulmonary disease (COPD)." (PMID 26646719, 2015). "Although MMP-9 is recognized as key factor involved in asthma-associated structural changes of airway, detailed mode of its action remains unclear." (PMID 25650123, 2015). "However, one study reported heightened inflammation in MMP9-deficient mice, which suggests a protective role of MMP9 in classic asthma." (PMID 25187823, 2014). "In addition, we only included term infants, precluding bias, since asthma is associated with prematurity which may be related to MMP‐9." (PMID 40952045, 2026). "Notably, MMP9 is equally associated with Th2-mediated acute inflammation in asthma." (PMID 38974913, 2024). "Therefore, we performed a meta-analysis of all eligible studies to obtain more precise estimation of the association of MMP-9 gene polymorphisms including three SNPs (−1562 C > T, rs3918242; Gln279Arg, rs17576, and Arg668Gln, rs17577) with asthma susceptibility." (PMID 30931075, 2019). "In conclusion, the current meta-analysis indicates that the MMP-9 −1562 C > T, rs3918242 and Gln279Arg, rs17576 polymorphisms are not the independent risk factor for asthma susceptibility; however, the Arg668Gln, rs17577 polymorphism is the risk factor for asthma susceptibility." (PMID 30931075, 2019). "Finally, in addition to the usefulness of MMP-9/EBC measurement as a risk marker, the confirmation of pivotal role of MMP-9 in asthma-associated remodeling may have another potential benefit." (PMID 25650123, 2015). "Since IL-4, LIGHT, LTBR, TGFβ, MMP-9, and NO are key mediators involved in the pathogenesis of allergy and asthma, the increase in their expression may contribute to the increased vulnerability and risk of asthma in the obese." (PMID 25642424, 2015). "Plant-derived active components, such as green tea extract, can alleviate airway inflammation and remodeling by inhibiting the expression and activity of MMP-9, suggesting the potential of natural products in asthma treatment." (PMID 41599256, 2026). "Topological analysis examined node centrality (degree, betweenness) to identify critical targets, exemplified by a study on andrographolide asthma, where IL-6/MMP9 hubs and Th17 pathways were validated." (PMID 40732361, 2025). "The transcriptome found significantly elevated MMP9 in bronchial epithelium in asthma and COPD, and alveolar lavage fluid in asthma also confirmed significant upregulation of MMP9 in moderate and severe asthma." (PMID 40160461, 2025). "TGF-β1 is a well-established pro-fibrotic cytokine involved in subepithelial fibrosis and smooth muscle hyperplasia in asthma, while the MMP-9/TIMP-1 balance reflects extracellular matrix turnover." (PMID 41181185, 2025).